FN1 (fibronectin 1)
Diseases named in the same sentence as FN1 in open-access papers (continued):
Sharing a sentence is not in itself a finding about the gene and the disease.
non-small cell lung carcinoma (15 papers, 2014 to 2025). A group of at least three distinct histological types of lung cancer, including non-small cell squamous cell carcinoma, adenocarcinoma, and large cell carcinoma. "It has been reported that FN1 can increase cisplatin resistance in non-small cell lung cancer by modulating β-catenin signaling via interaction with integrin-β1." (PMID 33439992, 2021). "Han and colleagues found that FN1 stimulated non-small cell lung cancer cell proliferation by activating the mammalian target of rapamycin, mTOR." (PMID 33962392, 2021). "Recent findings in non-small cell lung cancer cell lines indicate that phospho-Erk1/2 mediates a decrease in ECad and an increase in FN1 expression." (PMID 26187636, 2015). "The growth-promoting effect of FN1 has been explored in non-small cell lung carcinoma cell." (PMID 26646797, 2016). "Bioinformatic analyses have demonstrated that EGFR, KDR, FN1, TGFB1 as well as PCNA are interacting with VEGF-A and are involved in non-small cell lung cancer tumorigenesis." (PMID 35252204, 2022). "FN1, together with E-cad and VIM, serves as a marker for EMT in non-small cell lung cancer." (PMID 32697311, 2020).
heart failure (14 papers, 2020 to 2025). Inability of the heart to pump blood at an adequate rate to meet tissue metabolic requirements. "In addition, as shown in the volcano plot, the levels of active fibroblast markers (POSTN, THBS4, CILP, and FN1) were increased in the heart failure group." (PMID 39198543, 2024). "In addition, we found that active fibroblast markers (POSTN, THBS4, CILP, and FN1) were significantly elevated in the heart failure group." (PMID 39198543, 2024). "The roles of COL1A1 and FN1 in heart failure were previously well explored." (PMID 37450589, 2023). "Furthermore, we observed the proportion of markers associated with fibroblasts (VIM, POSTN, DDR2, THBS4, COL1A1, COL1A2, FN1) were significantly higher in heart failure than the control group in the human data, which were consistent with that in mice." (PMID 36805782, 2023). "We found that FN1 was significantly upregulated in the atrial fibrillation (P < 0.05), heart failure (P < 0.01), hypertrophic cardiomyopathy (P < 0.001), chronic kidney disease (P < 0.05), focal segmental glomerulosclerosis (P < 0.01), and uremia (P < 0.001) samples compared with control samples." (PMID 35133974, 2022). "FN1 inhibition attenuates fibrosis and improves cardiac function in a model of heart failure." (PMID 33233425, 2020). "In human heart failure, single-cell transcriptomic profiling revealed a marked expansion of SPP1+ macrophages, co-expressing markers such as FN1 and TREM2, and occupying fibrotic niches where they orchestrate ECM remodeling through CXCL4 signaling." (PMID 40900730, 2025). "Several subpopulations of fibroblasts such as fibroblast-THBS4, fibroblast-FN1, fibroblast-POSTN were also found in human heart increasing with heart failure, which is consistent with our results in mice." (PMID 36805782, 2023). "Consistent with above data, cluster 1 (subtypes with high expression of extracellular matrix protein including DDR2, THBS4, FN1, POSTN) at heart failure which involved in ECM organization, extracellular structure organization." (PMID 36805782, 2023). "FN1 participates in ECM remodeling and its inhibition attenuates fibrosis and improves heart failure." (PMID 33810615, 2021). "A systems transcriptomic study identified fibronectin-1 (FN1) and periostin (POSTN) as hub genes during CRS progression in rats, and importantly, these were found to be highly expressed across numerous human heart failure and kidney disease datasets as well." (PMID 41300756, 2025).
lymph node metastasis (14 papers, 2018 to 2025). "However, it is inversely associated with lymph node metastasis, high-grade tumors, and FN1 (fibronectin 1) expression, while positively correlated with favorable outcomes in patients with triple-negative breast cancer." (PMID 39684286, 2024). "Moreover, studies have reported that FN1 is overexpressed and associated with lymph node metastasis in PTC." (PMID 33738254, 2021). "FN1 expression positively correlated with all parameters of advanced disease: lymph node metastasis, advanced stage, and extrathyroidal extension (for all P < 0.0001)." (PMID 40423510, 2025). "The ROC curve results showed that FN1 mRNA had better accuracy in differentiating lymph node metastases." (PMID 37026938, 2023). "FN1 performed well in discriminating between patients with lymph node metastases (N1) and N0 with an AUC of 0.690." (PMID 36418670, 2023). "FN1 showed good results in distinguishing patients with lymph node metastases (N1) from N0." (PMID 36418670, 2023). "Whether FN1 can be used as a biomarker for lymph node metastasis requires more experiments to verify." (PMID 37026938, 2023). "Elevated FN1 expression, and to a lesser extent ITGAV, correlated positively with lymph node metastasis, advanced cancer stages, extrathyroidal extension, and poorer prognoses." (PMID 40423510, 2025). "The current study revealed FN1, MMP9, and CXCL8 as potential biomarkers for identifying and predicting lymph node metastases." (PMID 37640804, 2023). "Moreover, the expression of FN1 is elevated in the PTC patients with lymph node metastasis (LNM) compared with the patients without LNM, and overexpression of FN1 is associated with PTC in larger tumor size and an advanced stage." (PMID 33669363, 2021). "Finally, we performed a LASSO logistic regression analysis of the gene expression matrix of seven of the THCA cohort from the TCGA database by the presence or absence of lymph node metastasis to finalize the risk scores constructed for the five most relevant genes (EVA1A, SERPINA1, FN1, TNC, MXRA8)." (PMID 35141140, 2021).
renal cell carcinoma (14 papers, 2007 to 2025). "A previous study showed that FN1 mRNA expression in renal cell cancer was higher than that in normal renal tissue." (PMID 36009866, 2022). "Similarly, high expression of FN1 may be a positive tumor biomarker contributing to invasive breast cancer, pancreatic ductal adenocarcinoma (PDAC), and renal cell carcinoma (RCC)." (PMID 38737262, 2024).
glomerulopathy (13 papers, 2012 to 2025). "Certain heterozygous mutations in FN1 have been proposed to cause or contribute to disease, including glomerulopathy and spondylometaphyseal dysplasia." (PMID 36268024, 2022). "FN1 is involved in the development and progression of various diseases, including spondyloepiphyseal dysplasia, corner fracture type and glomerulopathy with fibrin deposition." (PMID 36118693, 2022). "(a) NM_003647.2(DGKE):c.953A>G, p.N318S (MIM#601440), nephrotic syndrome, type 7 (MIM#615008, AR), homozygous.(b) NM_212482.2(FN1):c.5587C>T, p.P1863S (MIM#135600), glomerulopathy with fibronectin deposits 2 (MIM#601894, AD), heterozygous." (PMID 41477467, 2025).
metastatic tumors (13 papers, 2012 to 2025). "We found that the expression profile of the prognostic marker genes: CA9, VEGFA, and FN1, observed in in vivo orthotopic and metastatic tumor datasets was similar to the patient tumor datasets, whereas FN1 was only upregulated in the in vitro cell culture dataset." (PMID 40241258, 2025). "Further investigation to decipher microenvironmental cues favoring FN1-integrin pathways are needed to identify key signaling components that participate to dormant cell reactivation, offering new targets and therapeutic agents to fight metastatic disease." (PMID 33731188, 2021). "Notably, in our prior work utilizing primarily PDAC mouse models with advanced metastatic disease, CTCs shared expression of ECM associated genes including FN1 and SPARC10,11, implying multiple potential drivers of these pro-metastatic markers." (PMID 32620742, 2020). "Thus, if we can inhibit mesothelial conversion to OCAMs or inhibit the FN1/Akt signaling pathway axis, we may be able to effectively control the development of peritoneal metastatic tumors even with the use of conventional platinum‐based chemotherapy." (PMID 31904865, 2020). "FN1, one of the most abundant glycoproteins in the ECM, is expressed not only in the stroma but also in tumor cells and exerts a significant role in tumor progression, invasion and premetastatic and metastatic disease mainly through integrin-mediated signaling." (PMID 36333284, 2022).
oral squamous cell carcinoma (13 papers, 2015 to 2024). "In oral squamous cell carcinoma, upregulated FN1 was linked to a dismal prognosis and resulted in lymphangiogenesis, along with lymph node metastases." (PMID 36059672, 2022). "The elevated expression of FN1 promotes lymph node metastasis in human oral squamous cell carcinoma by promoting vascular endothelial growth factor-C expression and the epithelial–mesenchymal transition (EMT)." (PMID 30237810, 2018). "Similarly, LINC01116 promotes the progression of oral squamous cell carcinoma through miR-136-mediated FN1 overexpression." (PMID 33762953, 2021). "For instance, FN1 increased the expression of VEGF to promote EMT and lymph node metastasis through FAK activation in oral squamous cell carcinoma." (PMID 36151071, 2022).
osteoarthritis (13 papers, 2012 to 2025). A noninflammatory degenerative joint disease occurring chiefly in older persons, characterized by degeneration of the articular cartilage, hypertrophy of bone at the margins and changes in the synovial membrane. "The FN1 gene has also been studied as one of the major genes responsible for osteoarthritis in some species, such as mice, and even in humans." (PMID 38788487, 2024). "Results from both qRT‐PCR and western blot showed that in the osteoarthritis group, FN1 and collagen III expression levels were, respectively, 42% and 58% lower than in the healthy control group (P < 0.01)." (PMID 30560591, 2019). "In a mouse model of the medial meniscus, Fn1 was a hub in a reconstructed network in osteoarthritis with the transcriptional analysis." (PMID 30560591, 2019). "Besides, MicroRNA-183 regulates LPS-induced oxidative stress by targeting FN1 and MicroRNA-140-3p can ameliorate the progression of osteoarthritis via targeting CXCR4." (PMID 35281834, 2022). "Meanwhile, we tested the expression of FN1 and collagen III, which were all related with osteoarthritis." (PMID 30560591, 2019).
Stroke (13 papers, 2011 to 2025). Sudden impairment of blood flow to a part of the brain due to occlusion or rupture of an artery to the brain. "FN1 has been associated promotion of angiogenesis, neural crest cell migration and is neuroprotective in stroke and traumatic brain injury." (PMID 24244468, 2013). "New genes to be considered for vascular restoration after stroke included Col6a3, Fn1, and Lamc1." (PMID 24672479, 2014). "Elevated levels of FN1 and MMP9 predicts endothelial damage and hemorrhage after stroke in response to thrombolytic therapy." (PMID 33668216, 2021). "Of therapeutic relevance, PSTG2 (COX-2) inhibitor celecoxib was found to lower FN1 and COL1 expression and attenuate the vessel wall thickness in stroke-prone spontaneously hypertensive rats." (PMID 29706885, 2018). "After stroke, high levels of MMP9 and Fn1 may represent severe damage to neurovascular units." (PMID 34630032, 2021).
Alzheimer disease (12 papers, 2016 to 2025). A progressive, neurodegenerative disease characterized by loss of function and death of nerve cells in several areas of the brain leading to loss of cognitive function such as memory and language. "FN1 emerged as a particularly intriguing mediator, as it is upregulated in both sporadic and genetic forms of cSVD36–38, yet rare loss-of-function variants in FN1 protect against Alzheimer’s disease in APOE4 homozygotes." (PMID 41279343, 2025). "The FN1+ MG subcluster exhibits high expression of the Alzheimer’s disease risk genes ABI3, CD33, and PTK2B, suggesting that this component of CSF microglia-like cells could emerge from a specific myeloid cell response to protein aggregates accumulating in the parenchyma during neurodegeneration." (PMID 39744938, 2025). "Fn1 is a biomarker of the inflammatory response and is also regarded as an indicator of Alzheimer's disease progression." (PMID 33628784, 2021).
clear cell renal cell carcinoma (12 papers, 2009 to 2023). "For instance, IGF2BP3 enhanced the proliferative activity of clear cell renal cell cancer cells by increasing the expression of cyclin-dependent kinase 4, collagen type VI alpha 1 chain, laminin subunit alpha 5, and fibronectin 1 in an m6A-dependent manner." (PMID 34621671, 2021). "FN1 (15th by MUFFINN yet below 8000th by the gene-centric methods in clear cell kidney carcinoma (KIRC) samples) is a novel fusion partner of ALK in myofibroblastic tumors." (PMID 27333808, 2016). "In clear cell renal cell carcinoma, the complex of IGF2BP3/lncRNA DMDRMR selectively interacts with their m6A-modified co-targets (including CDK4, COL6A1, LAMA5, and FN1) to promote cell proliferation." (PMID 37280679, 2023). "In clear-cell renal cancer, eight differentially expressed genes were identified as biomarkers, including VEGFA, FLT1, FN1, and others." (PMID 32070055, 2020). "In clear cell renal cell carcinoma (ccRCC), miR-204-3p was found to be down-regulated by the ERβ-suppressed circular RNA ATP2B1, which increased the expression of fibronectin 1 and promoted the invasion of ccRCC cells." (PMID 31850191, 2019).
preeclampsia (12 papers, 2012 to 2025). Preeclampsia is a hypertensive disorder of pregnancy that is characterized by new-onset hypertension with proteinuria presenting after 20 weeks of gestation, and depending on mild or severe forms may initially present with severe headache, visual disturbances, and hyperreflexia. "Among these genes, LAMB2, PTK2, RAC1, QSOX1, FN1, and VCAM1 have known associations with the pathogenic mechanisms of preeclampsia." (PMID 35719905, 2021). "Fibronectin 1 (FN1) might promote the development of preeclampsia by modulating differentiation of human extravillous trophoblasts, as well as formation of focal adhesions." (PMID 35719905, 2021). "Among them, fibronectin 1 (FN1), a marker of vascular injury previously reported to be elevated in preeclamptic patients, and lactate dehydrogenase A (LDHA), whose serum levels have been suggested as a marker of preeclampsia and disease severity." (PMID 41446579, 2025). "Renal gene expression of Hsd11b2, Sgk1, Scnn1a, Nox4, and Fn1 was not different between mice who had a normal pregnancy and mice who had a preeclampsia-like pregnancy at 5 or 10 weeks postpartum (respectively)." (PMID 40425613, 2025).
esophageal cancer (11 papers, 2017 to 2025). A primary or metastatic malignant neoplasm involving the esophagus. "Authors of a recent study found that FN1 was associated with tumorigenesis of esophageal carcinoma as its overexpression correlated with a higher pathological stage of EC." (PMID 34795689, 2021). "Dysregulated FN1 was identified in obese adipose tissue while high FN1 expression was associated with esophageal cancer." (PMID 32999719, 2020). "Immunohistochemical analysis reporting elevated FN1 expression has been reported in various cancers, including breast, lung, thyroid and esophageal cancer." (PMID 33962392, 2021). "There was a significant positive correlation between LTBP1 and FN1 expression in esophageal carcinoma (r = 0.6, p < 0.001, spearman correlation analysis)." (PMID 32216815, 2020). "In conclusion, SATB1 is an oncogenic gene involved in esophageal cancer tumor cell proliferation and metastatic potential regulation; its function is partially delivered by the downstream genes FN1 and PDGFRB." (PMID 28147311, 2017). "In summary, we provided the first molecular evidence that SATB1 played an oncogenic role in esophageal cancer by up-regulation of FN1 and PDGFRB." (PMID 28147311, 2017). "A recent study showed that both cell adhesion molecules and ECM components OPN (SPP1) and FN1 might work as biological markers of progression and prognosis in esophageal cancer." (PMID 35252204, 2022). "The overexpression of FN1 or PDGFRB also enhanced the cell proliferation and migration ability, highlighting the importance of these two gene in esophageal cancer cells proliferation/invasion although the underlying mechanisms remains unknown." (PMID 28147311, 2017). "FN1 and PDGFRB are highly expressed in human esophageal cancer and play significant roles in promoting cell proliferation and migration." (PMID 40071088, 2025). "• Upregulates fibronectin 1 (FN1) and platelet-derived growth factor receptor beta (PDGFRB) in esophageal cancer." (PMID 40071088, 2025). "Network analysis and functional experiments further identified FN1 and PDGFRB to be key downstream genes regulated by SATB1 in esophageal cancer cells." (PMID 28147311, 2017). "To further explore the clinical significance of FN1 and PDGFRB expression in human esophageal cancer patients, we performed the online database analysis (Oncomine) to examine their expressions in human esophageal cancer patients." (PMID 28147311, 2017). "FN1, TNF, and IL-6 may be potential target genes regulated by APE1 in esophageal cancer." (PMID 40330011, 2025). "Importantly, FN1 and PDGFRB were found to be highly expressed in human esophageal cancer." (PMID 28147311, 2017).
lung adenocarcinoma (11 papers, 2020 to 2025). A carcinoma that arises from the lung and is characterized by the presence of malignant glandular epithelial cells. "Importantly, elevated FN1 expression demonstrated clear association with adverse patient outcomes, independently validating its role as a clinically relevant prognostic biomarker in lung adenocarcinoma." (PMID 41301482, 2025). "For example, circ-CAMK2A can target the pathway constituted by miR-615-5p and fibronectin 1 to exert a promoting impact on lung adenocarcinoma metastasis." (PMID 36803975, 2023). "It was found that high expression of FN1 and THBS1 was associated with low survival rates in patients with lung adenocarcinoma and lung squamous carcinoma." (PMID 36567906, 2022). "For example, down-regulation of miR-206 modulates in human lung adenocarcinoma epithelial cell line (A549’s) increase in the translation of fibronectin 1 through direct binding to the 3’UTR of the fibronectin 1 gene." (PMID 34359876, 2021). "The relationship between FN1 and THBS1 and the survival rate of patients with lung squamous carcinoma and lung adenocarcinoma were also analyzed using the GEPIA database." (PMID 36567906, 2022). "GEPIA revealed distinct clinical implications for FN1 and CCND1 in lung adenocarcinoma." (PMID 41301482, 2025). "Notably, we observed pronounced eCAF activity in both COLLAGEN and FN1 signaling, suggesting that eCAFs may enhance ECM density in lung adenocarcinoma and foster an immune-suppressive niche." (PMID 40657391, 2025).
myeloma (11 papers, 2015 to 2025). "These receptors were also shown to mediate binding and internalization of EVs by glioblastoma or myeloma cells through their interactions with EV-associated fibronectin (FN1)." (PMID 33816490, 2021). "It has been demonstrated that FN1 is present on the surface of myeloma cell-derived EVs and can serve as a heparan-binding ligand, which facilitated EV-target cell interactions." (PMID 31454892, 2019). "The expression of FN1 was reported to be significantly accumulated in vincristine-resistant myeloma cells, while other ECM components, including type II collagen α1, were downregulated." (PMID 25824986, 2015). "In other studies, heparan sulfates on myeloma cell-derived EVs were shown to capture FN1 which was then delivered to target cells via its subsequent binding to cell surface heparan sulfate receptors, resulting in activation of p38/pERK and expression of genes that promote myeloma progression." (PMID 33816490, 2021).